FAS (Fas cell surface death receptor)
Diseases named in the same sentence as FAS in open-access papers (continued):
Sharing a sentence is not in itself a finding about the gene and the disease.
tumor (continued). "We also observed that FAS was expressed in nearly twice as much tumor cells in ER-negative tumors, compared to ER-positive tumors, which also explains the higher expression of FAS in younger patients, since those are more often ER-negative." (PMID 28121628, 2017). "Another protein on tumor cells that determines function of T cells is Fas cell surface death receptor, abbreviated as FAS." (PMID 28121628, 2017). "In the remaining 640 patients, FAS expression was observed ranging from 0% to 100% of the tumor cells, with a median expression of 13.3%." (PMID 28121628, 2017). "FAS expression was determined using immunohistochemistry and the percentage of FAS-positive tumor cells was quantified." (PMID 28121628, 2017). "ER-negative tumors showed almost a doubling of the average expression of FAS compared to ER-positive tumors (37% vs 19% FAS-positive tumor cells per sample, p<0.05))." (PMID 28121628, 2017). "We evaluated tumor expression of FAS, a key receptor in T-cell mediated apoptosis, as possible explanation for this differential prognostic value of TILs." (PMID 28121628, 2017). "First, if FAS is activated by soluble FasL following its shedding from the surface of immune effector cell in the tumor microenvironment." (PMID 27843441, 2016). "A previous study demonstrated that IL-6 release induces a neutrophil-dependent anti-tumor response and that IL-6 is important in helping neutrophils resist FAS pathway-induced apoptosis." (PMID 27259252, 2016). "For example transgenic expression of IL-12 in CAR T cells reverses the immunosuppressive tumor environment by triggering apoptosis of inhibitory tumor-infiltrating macrophages, DCs, and MDSCs through a FAS-dependent pathway." (PMID 24427741, 2013). "Then, tumor cells can evade or weaken the immune system’s ability to eliminate them through the FAS-FASL pathway." (PMID 24014103, 2013). "Decreased expression or mutation of the FAS gene and/or increased expression of FASL have been reported to occur in many malignant tumors, supposedly impairing the sensitivity of tumor cells to apoptotic signals." (PMID 24014103, 2013). "The role anticancer-drug-induced FAS/FASL system in tumor-cell killing has been championed by some, it is currently however often disregarded as experimental artifact." (PMID 23326385, 2013). "For example many tumor cells express FAS-L, and silencing FAS in T cells prevents FAS-induced apoptosis." (PMID 24427741, 2013). "Multivariate analysis of the relationship between clinical, pathological tumor features and survival with FAS and FASL expression." (PMID 23894399, 2013). "Further the authors also revealed that Ad-MMP-2 mediated tumor growth inhibition occurred through cleavage of caspases-8,-9 and -3, and activation of FAS-mediated signaling pathway." (PMID 22962598, 2012). "In the present study, we observed a dose dependent upregulation of FAS after 4a treatment in both cell lines and mouse tumor models." (PMID 22970136, 2012). "The induced anti-tumor activity was well correlated with FAS expression, caspase-3 activation, and cancer cell apoptosis." (PMID 22295090, 2012). "Tumor-exosomes affect T cells by inducing FAS-mediated apoptosis and by enzymatic activity, which leads to extracellular adenosine production negatively modulating tumor infiltrating leukocytes (TIL)." (PMID 23190502, 2012). "The tumor volume measurement results were correlated well with FAS expression, caspase-3 activity, and TUNEL staining results." (PMID 22295090, 2012). "The TUNEL-positive cells coincided with FAS expression, indicating that the tumor cell death observed is due to apoptosis." (PMID 22295090, 2012).
tumor (continued). "We observed that FAS gene expression was down regulated in liver metastases beginning from day 10 after tumor cell injection following an initially increased expression." (PMID 20205946, 2010). "FAS has little effect on normal cells because they take up dietary lipids but, in tumor cells, FAS is upregulated and contributes to angiogenesis; thus THL is currently a lead compound in the development of anticancer drugs." (PMID 19169353, 2009). "According to previous reports, FAS expression was progressively decreased during tumour progression from normal epithelium to adenocarcinoma, which leads to conclude that other factors rather than receptor expression alone influence cell sensitisation." (PMID 17551494, 2007). "Sensitivity to apoptosis was correlated to the RNA expression levels of the DR4, DR5 and FAS in the established cell lines, an analysis that was extended to the primary tumours and their respective normal mucosa as well as their respective mouse xenografts." (PMID 17551494, 2007). "On the contrary, FAS expression was upregulated in tumour 14 (PAP60) compared with the receptor downregulation observed in tumour 15 (MIH55), which also correlated to the increased sensitivity of PAP60 tumour-derived cells to FASL." (PMID 17551494, 2007). "FAS expression analysis showed higher expression in the PAP60 original parental tumour as compared with its normal mucosa, whereas the opposite expression pattern existed in the MIH55 parental tumour." (PMID 17551494, 2007). "Further assessment demonstrated that the expression of necroptosis-related genes, including FADD, MLKL, TLR2, PGAM, HMGB1, CXCL 1, TRAF2, and EZH2, was elevated in tumor tissue, while FAS, RIPK1, RIPK3, TLR3, TNFRSF, ALDH2, and NDRG2 were upregulated in normal intestinal tissues." (PMID 40959081, 2025). "Similar results were observed for FAS, which is regarded as an anti-tumor neutrophil marker." (PMID 40867260, 2025). "Tumour-intrinsic IFNG expression upregulated HLA-ABC and increased FAS and PD-L1 in three out of four conditions, with similar effects in pre-sort and enriched cells, indicating that even low expression levels can trigger tumour-wide marker upregulation." (PMID 41366257, 2025). "NK cells exert their antitumor effects through a variety of mechanisms, including the recognition of stress-induced ligands on tumor cells, the release of cytotoxic granules, and the induction of tumor cell apoptosis via death receptors such as FAS and TRAIL-R2." (PMID 41102150, 2025). "In the immunogenic model RLS40, DNase I had anti-tumor, antimetastatic, and immunostimulatory effects and significantly modified the neutrophil profile by decreasing the expression of the immunosuppressive markers (Il10, Ccl17) and increasing the expression of the anti-tumor markers (PD-L1, FAS)." (PMID 40867260, 2025). "However, while KRASG12C primarily exerts this effect through the upregulation of PD-L1 on tumor cells, the opposite result is observed in G12D tumors, which instead attenuate T cell cytotoxicity by downregulating FAS expression." (PMID 40611261, 2025). "Following cross-presentation and costimulation primarily by cDC1 in secondary lymphoid organs, naïve CD8+ T cells become activated and migrate to tumor sites, where they directly eliminate tumor cells through perforin/granzyme-mediated or FAS/FASL-mediated cytotoxicity." (PMID 40860134, 2025). "Additionally, we observed that ARID1A mutant FL showed significantly lower FAS protein expression in the FL tumor cell population." (PMID 39843653, 2025). "In the RLS40 model, the neutrophil phenotype was associated with the tumor growth rate, where, in aggressively progressed tumors (RLS40High), CCL17 was expressed, while, in mice with controlled tumor growth (RLS40Low), anti-tumor markers were expressed (FAS, ICAM-1, PD-L1)." (PMID 40867260, 2025).
tumor (continued). "Expression data in GEPIA also showed that the expression of FAS was lower in tumor tissues compared with normal lung tissues in both LUAD (TPM =12.17 in tumor tissues and 28.41 in normal tissues) and LUSC (TPM =10.16 in tumor tissues and 29.52 in normal tissues)." (PMID 39416461, 2024). "In tumor cells, immune stimulation revealed an interplay of both immune activating and inhibitory signals, including up-regulation in immune-activating signals such as the FAS death receptor gene and the NK-activating ligand MICB." (PMID 39475596, 2024). "We also find that trNK may also recruit CD4+ Tregs via IL-16 but concomitant FAS signaling would lead to Treg apoptosis and support tumor control." (PMID 39656086, 2024). "The availability of genetic data in online tumor databases could provide useful information on the characteristics and potential role of FAS gene expression as a prognostic biomarker in cancers." (PMID 39416461, 2024). "Low or absent expression of DR4, DR5, and FAS was significantly associated with advanced tumor stage and muscle-invasive disease (p < 0.001, p = 0.33, and p = 0.25, respectively)." (PMID 38791085, 2024). "IFN‐γ may lead to tumor cell apoptosis directly or indirectly by upregulating the expression of FAS and DR5." (PMID 39003635, 2024). "The interaction between FAS on malignant cells and FASL on CD8+ T cells triggers a signal that activates the FAS-associated death domain protein, resulting in caspase activation and subsequent apoptosis of tumor cells." (PMID 39072335, 2024). "They found that BVC not only enhances the immune recognition between CD8 + T cells and FAS-overexpressing tumor cells but also reduces tumor cell immune escape through PD-1/PD-L1 blockade, resulting in significant benefits for the eradication of metastatic tumors." (PMID 38459595, 2024). "It was found that FAS expression decreases with progressive tumor stage." (PMID 38791085, 2024). "Resistance to apoptosis due to the FAS blockade may play a significant role in tumorigenesis and tumor progression." (PMID 38791085, 2024). "Transfection of the FAS gene into LM7 cells leads to decreased tumor formation in nude mice." (PMID 37569529, 2023). "In addition, a diet with high glycemic index and glycemic load levels induces inactivation of the FAS pathway, which regulates cell growth, proliferation, migration, differentiation, and apoptosis, leading to tumor growth." (PMID 37513656, 2023). "Some important ceRNAs, such as FAS and hsa-miR-125b-5p, and tumor-infiltrating immune cells might relate to distance metastasis and prognosis of Colon Adenocarcinoma Metastasis." (PMID 36875764, 2023). "The upregulation of FAS potentiated by radiotherapy in combination with intratumoral injection of TGFβ-MDSC could generate a long-lasting tumor immune response with potential benefit to survival." (PMID 37232820, 2023). "In summary, the negative correlation between FAS methylation of CGI shores and expression observed among tumor samples suggests that methylation of this region may be responsible for regulating FAS gene expression." (PMID 37569529, 2023). "However, for an effective cytotoxic effect of tumor cells to occur, it is necessary that tumor-infiltrating TCD8s bind FAS/FASL to induce cell apoptosisn." (PMID 38219446, 2023). "Therapeutic targets that re-express FAS in tumor cells may promote increased interaction with FASL and reduction in development of lung metastasis in OS." (PMID 37569529, 2023). "As a tumor suppressor, the FAS pathway plays an important role." (PMID 37513656, 2023). "FAS was demonstrated to be increased in tumor samples in our investigation, and its high expression in PTC patients predicted better survival, implying that FAS may be a tumor suppressor gene." (PMID 36186479, 2022). "FAS expression was positively associated with CD18, CD47 and IRF47, which suggested that FAS may also help the migrated tumour cells survive from the immune surveillance." (PMID 35685372, 2022).
tumor (continued). "Furthermore, FAS is also repressed by its promoter H3K9me3 deposition in human colon-tumor cell lines, especially the metastatic human colon-tumor cells." (PMID 35053524, 2022). "All FAS+ tumor cells were effectively eliminated by FASL in vitro." (PMID 35053524, 2022). "Moreover, FAS-dependent tumor killing by CAR-T is augmented by inhibiting or knocking out anti-apoptotic regulators or by increasing pro-apoptotic regulators of the FAS signaling pathway." (PMID 35053524, 2022). "Genetic knockout of FAS or IFNGR1 in 5T4+ tumor cells abrogated tumor cell kill." (PMID 36271507, 2022). "Additionally, irradiation can induce an upregulation of FAS molecules on tumor cells, thereby improving the cytotoxic efficacy of T cells." (PMID 36358718, 2022). "Although CTCL cells repress the expression of FAS, it could be epigenetically increased via the de-repression of the FAS promoter by DNA hypomethylation, which can enhance tumor cell apoptosis in patients with CTCL." (PMID 35408897, 2022). "It was reported that the FAS promoter is hypermethylated in human colon-tumor-cell lines in vitro." (PMID 35053524, 2022). "CAFs can disturb the anti-tumor activity of effector T cells by inducing the expression of immune checkpoint molecules, such as FAS/FASL and PD-1/PD-L1 or PD-L2, on their surface, followed by decreased CD8+ T cell frequency and activation and, in contrast, increased tumor cell viability." (PMID 36700220, 2022). "Polymorphisms in the FAS and FASL genes are associated with functional changes in the encoded proteins; among the polymorphisms studied, rs1800682 (FAS -670A/G) and rs5030772 (FASL -124A/G) were evaluated in the development of neoplasms and autoimmune inflammatory diseases, respectively." (PMID 36671466, 2022). "Our results thus indicate a tumour suppressor role of PTPN13 in the early stages of CRC growth, while in serosal invasion it may act as a tumour promoter via activation of Slug and Snail and inhibition of FAS-induced apoptosis." (PMID 36140249, 2022). "Multiple epigenetic mechanisms are involved in the silencing of FAS in the tumor cells." (PMID 35053524, 2022). "Also, when triggered by LIGHT, it will render tumor B cells higher immunogenicity and sensitivity to FAS-induced apoptosis." (PMID 35303910, 2022). "Known mechanisms responsible for FAS absence on the cell surface at the tumor site are transcriptional repression, promoter hypermethylation, histone acetylation m and generation of secreted soluble FAS proteins that lack the transmembrane domain via alternative mRNA splicing." (PMID 34771652, 2021). "Recent examples include knockdown of ACLY impairing pancreatic tumor formation and knockdown of FASN blocking tumor development in mTOR-driven liver cancer, while pharmacological inhibition of FAS reduced tumor growth in preclinical models of castration-resistant prostate cancer." (PMID 33413672, 2021). "KDM1A inhibitor doses as low as 0.5 μM could induce FAS expression on tumor cells, and FAS upregulation by the KDM1A inhibitor remained stable for up to 48 h after inhibitor removal, allowing subsequent T cell treatment to test combination therapy." (PMID 34771652, 2021). "Promoting tumor cytotoxicity mediated by FAS-FASL might improve the therapeutic efficacy of CAR T cells directed against tumors with heterogeneous antigen expression and present a way to overcome therapeutic failure due to antigen loss." (PMID 34771652, 2021). "In this research, we found some significant ceRNAs (FAS and hsa-miR-125b-5p) and tumor-infiltrating immune cells (T cells follicular helper and Macrophages M0) might related to distance metastasis and prognosis of COAD." (PMID 32850813, 2020).
tumor (continued). "Furthermore, PTPN13 repression mediated by miR-200 increases sensitivity to FAS-induced apoptosis in tumor cell lines with mesenchymal features (see chapter A)." (PMID 33322542, 2020). "Furthermore, FAS can induce pro-inflammatory responses, which resulted in tumor cell proliferation, invasion and metastasis." (PMID 31942177, 2020). "In resistant tumor cells, FAS also induces non-apoptotic signaling pathways linked to tumor growth, survival, and migration." (PMID 32260071, 2020). "FAS and T cells follicular helper are the significant ceRNA and tumor-infiltrating immune cell." (PMID 32850813, 2020). "Furthermore, over-expression of the miR-17-92 cluster, particularly miR-20a level was demonstrated to be involved in FAS suppression in OS cell lines that contributes to tumor cell survival and metastasis (lung metastases) in OS cells." (PMID 32565738, 2020). "Interestingly, it has been described that tumor-infiltrating T cells expressing IL-17 can induce B cells migration and increase FAS/FASL–dependent direct tumor cell killing by B cells." (PMID 31086070, 2019). "High expression of FAS is observed in many tumor types and these results indicated that curcumin might inhibit multiple tumor types via FAS inhibition." (PMID 31618928, 2019). "Since FAS signaling is involved in regulation of apoptosis and tumor proliferation, our findings might contribute to new therapeutic targets for ES." (PMID 29563856, 2018). "In addition, RT-induced upregulation of major histocompatibility complex class I molecules, FAS/CD95, and stress-induced natural killer group 2D-ligands on tumor cells enhance recognition and killing of cancer cells by cytotoxic T cells (CTLs)." (PMID 28348554, 2017). "Additionally, γδ T cells have been reported to induce tumour killing of FAS- and TRAIL-receptor-sensitive cancers to enhance the antibody-dependent cellular cytotoxicity (ADCC)." (PMID 28404796, 2017). "Therefore, three main aims of this study are identified: To evaluate the expression of FAS among different tumor subtypes in order to explain variances in the prognostic value of TILs." (PMID 28121628, 2017). "Aside from the pro-apoptotic effect on tumor cells, bortezomib can sensitize tumor cells to NK cells by decreasing expression of peptide–MHC class I complexes and increasing tumor cell surface expression of FAS and the TNF-related apoptosis-inducing ligand (TRAIL) receptor DR5." (PMID 29156850, 2017). "Furthermore, NLGP-influenced CD8+ T cells significantly reduce accumulation and suppressive potential of MDSCs by inducing FAS-mediated cell death, which ultimately favors immune surveillance to maintain the sustained tumor-free state." (PMID 28414726, 2017). "When FAS is differentially expressed among different tumor subtypes, it could be hypothesized that FAS is a key explanatory factor for the fact that TILs are prognostic in one subgroup, but not in other subgroups." (PMID 28121628, 2017). "It was shown that patients with a higher FAS-expression have a longer recurrence free and overall survival, even when corrected for age, histological subtype, tumor grade, tumor stage, ER-status, year of diagnosis, neo-adjuvant treatment, adjuvant chemotherapy and adjuvant endocrine therapy." (PMID 28121628, 2017). "Hypothetically, the expression of FASL by tumor cells could lead to induction of apoptosis in the cytotoxic T-cells which could be a second method of FAS-FASL-mediated immune evasion." (PMID 28121628, 2017). "The down-regulation of FAS may protect tumor cells from elimination by antitumor immune responses, whereas up-regulation of FASL may increase the ability of tumor cells to counterattack the immune system by inducing apoptosis of FAS-sensitive lymphocytes." (PMID 26858129, 2016). "FasL expression in tumor cells has been hypothesized as a “FAS counterattack,” by which tumor cells evade immune destruction by inducing FasL-mediated apoptosis in tumor-infiltrating lymphocytes." (PMID 25605245, 2015).